BRD4 (bromodomain containing 4)
Diseases named in the same sentence as BRD4 in open-access papers (continued):
Sharing a sentence is not in itself a finding about the gene and the disease.
prostate carcinoma (continued). "Anti-STEAP1 antibody-PROTAC conjugates with a BRD4 ligand and a VHL ligand, particularly STEAP1-5a (drug-to-antibody ratio (DAR) 6.0), afforded degradation of the BRD4 protein with a DC50 value of 0.67 nM using PC3-S1 prostate cancer cells." (PMID 37489365, 2023). "Hyperactive AR, in association with critical coactivators such as p300, BRD4, and MED1, drives prostate cancer progression." (PMID 37644036, 2023). "CDK4/CDK6 inhibitors have also been shown to exert synergistic anticancer effects with BRD4 inhibitors in castration-resistant prostate cancer and NUT midline carcinoma." (PMID 38135679, 2023). "In prostate cancer, mutated Speckle type POZ protein (SPOP) leads to impaired degradation and upregulation of BRD4 protein which confers intrinsic resistance to BET inhibitors." (PMID 36733715, 2023). "The last treatment predicted by CancerOmicsNet of the human prostate cancer cell line DU 145 with the ERK5/BRD4 inhibitor XMD8-92 (prediction score of 0.79) is effective only at the highest concentration of 10 μM." (PMID 37627077, 2023). "Recently, the BET family has been systematically explored as the treatment targets, and relevant inhibitors as antitumor agents have demonstrated remarkable clinical inhibitory effect, like JQ1 targeting BRD4 in prostate cancer." (PMID 35778964, 2023). "The conjugates exhibited intracellular delivery of the payloads to PC3-S1 prostate cancer cells along with reductions in intracellular BRD4 levels and in MYC transcription in vitro." (PMID 36770585, 2023). "In prostate cancer, BRD4 and MYC are direct substrates of SPOP, and the stabilization of BRD4 is directly linked to BETi resistance in prostate cancer cells carrying SPOP mutations." (PMID 37036970, 2023). "A study of BRD4 and prostate cancer states that ionizing radiation (IR) induces DSBs, which is repaired by BRD4." (PMID 35401196, 2022). "BRD4 plays an important role in multiple cancer types, such as prostate cancer, lung cancer, and hematological malignancies." (PMID 35958877, 2022). "BRD4 overexpression degrades AR and deregulates its expression, leading to prostate cancer or castration-resistant prostate development." (PMID 35401196, 2022). "Meanwhile, overexpression of SIPA1 downregulates Brd4, which further attenuates the binding between prostate cancer cells and ECM." (PMID 35431649, 2022). "SPOP-inactivating mutations in prostate cancer cells stabilize Brd4 and confer resistance to BETi, while SPOP-activating mutations in colorectal cancer cells with reduced Brd4 expression are exquisitely sensitive to BETi and prone to apoptosis." (PMID 36539410, 2022). "PROTAC 8 was thus expected to be developed as a promising drug candidate for AR-positive prostate cancer and a valuable tool compound to study the biological function of BRD4." (PMID 35702740, 2022). "A recent study reported that DUB3 binds to and promotes the deubiquitination and stabilization of BRD4 and protects prostate cancer cells from BETis by promoting BRD4 deubiquitination." (PMID 35402244, 2022). "Based on the encouraging anti-tumor activity of BRD4 inhibition in hematological malignancies and solid tumors such as prostate cancer, glioblastoma, neuroblastoma, and lung cancer, a number of BRD4 inhibitors have entered clinical trials for cancer treatment." (PMID 35453346, 2022). "JQ-1 displays antitumor effects in testicular germ cell tumors, leukemia, and prostate cancer by inhibiting BRD4, and BRD4 is a mediator of transcriptional elongation in the M/G1 cell cycle transition." (PMID 35118587, 2022). "In prostate cancer, SEs force the tumor cells to become addicted to dysregulated transcription programs mediated by proteins such as BRD4, CDK7, and ERG." (PMID 36408163, 2022). "In a previous study, BRD4 was identified as a biomarker for predicting poor prognosis for prostate cancer patients." (PMID 36276071, 2022).
prostate carcinoma (continued). "(2018) demonstrated that the BET protein BRD4 binds to acetylated histones following IR-induced DNA damage and associates with the NHEJ DNA repair protein Ku80 to increase DNA repair in prostate cancer models." (PMID 35795040, 2022). "ERG in conjunction with p300 activity recruits BRD4 at its target genes, leading to their transcriptional activation and supporting leukemia maintenance and prostate cancer cell invasion." (PMID 35267426, 2022). "In many cancer such as liver cancer, lung cancer, and prostate cancer, bromodomain‐containing protein 4 (BRD4) is a transcriptional and epigenetic regulator t playing a critical role during carcinogenesis and embryogenesis." (PMID 34173348, 2021). "The inhibition of cell migration by JQ1 in salivary adenoid cystic carcinoma (SACC), prostate cancer, etc. through the downregulation of BRD4 had been confirmed in previous studies." (PMID 34083693, 2021). "BRD4 plays important roles in a number of cancer types, including prostate cancer, lung carcinoma, and melanoma, as well as hematologic malignancies." (PMID 33888130, 2021). "In prostate cancer, specific SPOP mutation can also confer resistance to BET-BD inhibitors through stabilization of BRD4 and enhanced Akt–mTORC1 activation as a result of BRD4 stabilization." (PMID 34540900, 2021). "NCOR2 deletion leading to activation of DUB3 and BRD4 protein is often detected in castrated prostate cancer patients." (PMID 34454495, 2021). "In prostate cancer, BRD4 regulates cell migration along with infiltration through the transcription of AHNAK." (PMID 34689136, 2021). "BRD4 inhibition resulted in enhanced phosphorylated H2AX in prostate cancer cells because BRD4 is required for the repair of DNA DSBs induced by ionizing radiation." (PMID 33803654, 2021). "SNIPER(BRD4)-1 with LCL161 and JQ1 to recruit IAP E3 ligase and BRD4-induced BRD4 degradation at 3 nM in prostate cancer LNCaP cells." (PMID 32404196, 2020). "BRD4 inhibition has been validated and investigated in leukemia, lymphoma, myeloma, neuroblastoma, breast cancer, prostate cancer, and other cancer types." (PMID 33299103, 2020). "AR can also bind to the bromodomain of BRD4 to decrease the sensitivity of cancer cells to BET inhibitors in prostate cancer." (PMID 31718704, 2019). "The subgroup of BET proteins (bromodomain and extra-terminal), and in particular BRD4, have been the best characterized in prostate cancer, and several inhibitors of BET bromodomains have been developed and are currently in clinical trial." (PMID 29888169, 2018). "Many previous studies have shown that JQ1 induces cytotoxicity in a variety of cancers (e.g., multiple myeloma, leukemia, breast cancer, and prostate cancer) due to binding to BRD4 and preventing its interaction with several oncogenes." (PMID 29796168, 2018). "Recently, we have shown that bromodomain proteins such as BRD4 physically interact with the AR and are necessary for AR-mediated transcription in metastatic castration-resistant prostate cancer models." (PMID 25928204, 2014). "The enrichment of BRD4 in metastases suggests that it may be a factor in increasing cell proliferation and enhanced cell survival, as it has shown its capabilities along prostate cancer lines." (PMID 41154418, 2025). "However, aberrant activity of multiple other transcriptional regulators, including transcriptional cyclin-dependent kinases (CDKs), MYC and BRD4, is also critical for prostate cancer growth, metastasis and therapy resistance." (PMID 40163908, 2025). "Furthermore, previous studies in prostate cancer, triple-negative breast cancer, and cervical cancer found that the inhibition of BRD4 upregulates γH2AX and increases cell death, emphasizing the role of BRD4 in DNA repair." (PMID 40649963, 2025). "Moreover, the elevated expression of BRD4 significantly correlated with poor survival of prostate cancer patients." (PMID 40370549, 2025).
prostate carcinoma (continued). "BRD4 can be specifically inhibited to suppress growth and trigger apoptosis in a variety of cancerous cells, such as diffuse large B-cell lymphoma, breast and prostate cancer, and acute myeloid leukemia." (PMID 39323672, 2024). "Targeting BRD4 via BET inhibitors or proteolysis-targeting chimera (PROTAC) degraders suppresses prostate cancer development, and clinical evaluation of BRD4 inhibitors is under way in patients with castration-resistant prostate cancer (NCT02711956, NCT03150056)." (PMID 39146021, 2024). "BRD4 inhibitors have demonstrated promising results in both preclinical and clinical studies against various cancer types, including leukemia, lymphoma, and solid tumors such as breast, lung, and prostate cancers." (PMID 38473320, 2024). "In another study, other BRD4 degraders were conjugated by the same laboratory to an antibody against six transmembrane epithelial antigen of the prostate 1 (STEAP1) overexpressed in prostate cancer." (PMID 36770585, 2023). "In prostate cancer, BRD4 inhibitors block mitochondrial fission." (PMID 37237996, 2023). "We previously demonstrated that in prostate cancer, higher BRD4 proteins levels could confer resistance to JQ1." (PMID 37543638, 2023). "In prostate cancer, the loss-of-function mutation of SPOP (an E3 ubiquitin ligase of Brd4) has been shown to confer resistance to BET inhibitors by impairing ubiquitination-mediated Brd4 degradation." (PMID 37049806, 2023). "Given our recent findings of nuclear condensates between LSD1 and BRD4 driving super-enhancer activation in prostate cancer cells, it is plausible that EHMT1 may also participate in these complexes." (PMID 37663929, 2023). "Besides the phosphorylation, the speckle type BTB/POZ protein (SPOP)-mediated BRD4 ubiquitination regulates BRD4 degradation in prostate cancer." (PMID 37737256, 2023). "DUB3 binds to BRD4 to promote its deubiquitination and stabilization in prostate cancer." (PMID 34454495, 2021). "In the same way, prostate tumoroids have revealed that prostate cancer-associated SPOP mutations confer resistance to BET inhibitors through the stabilization of BRD4, enabling a deeper understanding of how prostate cancers of certain patients respond to treatment according to their genetic lesions." (PMID 34327198, 2021). "Moreover, in prostate cancer cells, elevated expression of bromodomain-containing protein 4 (BRD4, a member of BET family), induced by BETi, confers resistance to these inhibitors." (PMID 33997894, 2021). "Interestingly, a recent study shows that a proficient expression of deubiquitinase DUB3 in prostate cancer can promote BRD4 stabilization and resistance to BETi8." (PMID 34290255, 2021). "In addition, BRD4 interacts with the N-terminal domain of AR and induces AR-mediated gene transcription and BET inhibitor, JQ1 effectively disrupts the interaction between BRD4 and AR leading to cytotoxic efficacies in advanced prostate cancer model." (PMID 31527644, 2019). "Inhibition of either ZFX or BRD4 suppresses the growth of prostate cancer cells." (PMID 31366128, 2019). "Thus, Welti and coworkers explored BRD2, BRD3, and BRD4 expression at various stages of prostate cancer development." (PMID 31366128, 2019). "The luciferase reporter assay demonstrated that BRD4 is a direct target gene of miR‐200a and it could reverse miR‐200a‐mediated biological effects in prostate cancer cells." (PMID 30784214, 2019). "Previous studies have demonstrated that BRD4 can promote the transcriptional activities of oncogenic factors in prostate cancer by physically interacting with the N‐terminal domain of androgen receptor (AR), which is a crucial element of the AR signaling pathway." (PMID 30784214, 2019). "Interestingly, Hussong and colleagues have recently established a link between BRD4 and oxidative stress response genes in prostate cancer, such as the KEAP1/NRF2 axis and HMOX1, and reactive oxygen species (ROS) production." (PMID 29888169, 2018).
prostate carcinoma (continued). "Moreover, resistance to JQ1 itself has also been demonstrated through SPOP mutation, which contributes to resistance to BET inhibitors through BRD4 stabilization in prostate cancer." (PMID 29796168, 2018). "The role of BET proteins, mainly BRD4, in prostate cancer has been reported by several groups." (PMID 28486411, 2017). "This truncated fumaramide handle maintainedrobust degradation of BRD4 and expanded the scope of neo-substratetargets, including CDK4/6, SMARCA2/4, and notably, the androgen receptor(AR) and its therapeutically challenging truncation variant AR-V7in androgen-independent prostate cancer cells." (PMID 40726802, 2025). "Another study showed that excessive activation of BRD4 could promote epithelial-mesenchymal transition (EMT) in prostate cancer cells, thus promoting prostate cancer cell metastasis, which JQ1 could be used to effectively block this process, thereby exerting antitumor effects." (PMID 38410799, 2024). "Thus, BRD4 might represent a fine-tune modulator of the antioxidant response in prostate cancer by influencing the expression of HO-1 and interacting with the NRF2/KEAP1 network." (PMID 31097977, 2019). "Also, the epigenetic sensor BRD4 (bromodomain protein 4), an acetylated histone-binding protein implicated in transcriptional regulation, was found to regulate KEAP1 function in a model of prostate cancer." (PMID 31097977, 2019). "In addition, miR-200a might inactivate BRD4-mediated AR signalling to inhibit the progression of prostate cancer." (PMID 31842887, 2019). "While the most consistent and pronounced effects were observed following BRD4 knockdown, loss of BRD2 and BRD3 also inhibited LNCaP cell growth, suggesting that all three BET family proteins contribute to the potent growth responses to BET inhibitors observed in prostate cancer cell lines." (PMID 24293458, 2013). "Chromatin immunoprecipitation (ChIP) data confirm that SETD6 impacts the binding of E2F1 and BRD4 at the same target loci, establishing a novel mechanism by which SETD6 methylation of E2F1 modulates gene regulation programs in prostate cancer cells." (PMID 41540805, 2026). "To demonstrate the SETD6-dependent binding of BRD4 and E2F1 in cells, we performed a GFP-trap assay in DU145 prostate cancer cells." (PMID 41540805, 2026). "In PC3 prostate cancer cells and primary prostate cancer cells, AZD5153 induces apoptosis and down-regulates the expression of BRD4 target genes." (PMID 40859234, 2025). "Our study provides novel insight into the epigenetic regulation of metastatic dissemination in prostate cancer (PCa), identifying the BET family protein BRD4 as a key driver of the H19/cell adhesion molecule axis that promotes collective cell migration." (PMID 40407591, 2025). "In this review, we focus on the roles of transcriptional CDKs in prostate cancer growth, metastasis and therapy resistance and discuss their interplay with AR, MYC and BRD4." (PMID 40163908, 2025). "The BD2-selective inhibitor ABBV-744 (AbbVie) showed robust preclinical efficacy in AR-positive prostate cancer and AML models, displacing BRD4 from AR-containing super-enhancers, inhibiting AR-dependent transcription, and reducing tumor growth in xenografts." (PMID 41335282, 2025). "It is highly selective against BD2 of BRD2, BRD3, and BRD4 and has strong antiproliferative activity against AML and prostate cancer cell lines, with a very low half maximal inhibitory concentration (IC50)." (PMID 40650308, 2025). "ARV-825, another highly potent PROTAC BET degrader, has been shown to effectively target BRD4 in diffuse large B-cell lymphoma (DLBCL), multiple myeloma, and prostate cancer models." (PMID 41335282, 2025). "In conclusion, our study identifies a novel and clinically relevant regulatory axis in metastatic prostate cancer, wherein BET family proteins—particularly BRD4—function as central epigenetic effectors of the H19/cell adhesion molecule circuitry." (PMID 40407591, 2025).
prostate carcinoma (continued). "Here, we evaluate CDKI-73’s activity in prostate cancer and demonstrate that it promotes apoptosis and inhibits signaling by AR, MYC, and BRD4." (PMID 39117800, 2024). "Abnormal transcription activities driven by SEs, such as cyclin dependent kinase 7 (CDK7), bromodomain and extra-terminal domain (BET)/bromodomain containing 4 (BRD4), and androgen receptor (AR), have been reported to influence prostate cancer phenotypes." (PMID 38410974, 2024). "ARV-771 reduces cell proliferation and induces apoptosis substantially more effectively than the BRD4 inhibitor JQ1 and OTX015 in castration-resistant prostate cancer and diffuse large B cell lymphoma cells." (PMID 38135679, 2023). "In leukemia and prostate cancer cells, interaction between ERG and bromodomain containing protein 4 (BRD4) has been observed." (PMID 35267426, 2022). "In prostate cancer, the TMPRSS2‐ERG fusion protein was also shown to interact with BRD4 and with SWI/SNF." (PMID 35182012, 2022). "The sensitivity of prostate cancer cells to the BET inhibitor, JQ1, depends on the deubiquitinating effect of DUB3 on BRD4." (PMID 34454495, 2021). "Another photo-caged PROTAC4 induced BRD4 degradation in HEK293T cells and reduced the viability of prostate carcinoma 22Rv1 cells upon irradiation." (PMID 32404196, 2020). "MYC is a well-described BRD4 target gene in multiple cancer types, and prior work demonstrates that MYC plays an important role in promoting prostate cancer cell survival." (PMID 30846826, 2019). "Inhibitors targeting the bromodomains of BRD4 and related BET proteins show efficacy in preclinical prostate cancer models." (PMID 31200487, 2019). "AZD5153 mechanically and simultaneously connects to two BRD4 bromodomains, which is a different mechanism from the previous BRD4 inhibitors (such as JQ1), and exerts potent anti-tumor effects on a variety of cancers (such as hematological malignancies, prostate cancer, and colorectal cancer)." (PMID 40859234, 2025). "To investigate the clinical relevance of SLC22A3 downregulation in prostate cancers, we knocked out SLC22A3 in the prostate cancer C4-2 cell line to assess drug sensitivity to two clinically used anti-prostate cancer drugs, Enzalutamide (AR inhibitor) and JQ1 (BRD4 inhibitor)." (PMID 39858458, 2025). "They demonstrated that NEO2734, a dual inhibitor targeting both BRD4 and p300, suppresses CD318 transcription and its downstream signaling pathways, thereby inhibiting proliferation and metastasis in castration-resistant prostate cancer cells." (PMID 40725832, 2025). "This study demonstrated that BRD4 plays a fundamental role in direct activation of tumor lineage plasticity programs and that its inhibitor AZD5153 is highly promising in effective treatment of the lethal forms of prostate cancer." (PMID 40370549, 2025). "Third, beyond affecting the levels and phosphorylation of transcriptional regulators with central roles in prostate cancer growth and progression – AR, MYC, and BRD4 – CDKI-73 would blunt the oncogenic transcriptional programs activated by these factors via reducing pSer2-RNAPII." (PMID 39117800, 2024). "Induction of histone crotonylation with bromodomain-containing protein 4 (BRD4) inhibitors can inhibit the proliferation and migration of prostate cancer cells, suggesting histone crotonylation can serve as biomarker for the diagnosis of prostate cancer and a therapeutic target for the treatment." (PMID 39606030, 2024). "JQ1, a BRD4 inhibitor, has been reported to upregulate MHC-I expression in prostate cancer." (PMID 35517410, 2022). "Similarly, for prostate cancer, KDM1A, BRD4, and PRMT1 were depleted in LNCaP cells as well as AR, FOXA1 and NCOA1, thus serving as positive controls." (PMID 35973998, 2022). "Guan H reported that the BRD4/AR signaling pathway was significantly activated when progressing from ADPC to CRPC, and miR-200a could suppress prostate cancer progression by inhibiting this signaling pathway." (PMID 35184651, 2022).